CCDC61 (coiled-coil domain containing 61)
Description:
Microtubule-binding centrosomal protein required for centriole cohesion, independently of the centrosome-associated protein/CEP250 and rootletin/CROCC linker. In interphase, required for anchoring microtubule at the mother centriole subdistal appendages and for centrosome positioning. During mitosis, may be involved in spindle assembly and chromatin alignment by regulating the organization of spindle microtubules into a symmetrical structure. Has been proposed to play a role in CEP170 recruitment to centrosomes. However, this function could not be confirmed. Plays a non-essential role in ciliogenesis.
Synonyms: VFL3; hVFL3
Tractability: PROTAC: ubiquitination databases record sites on it; its protein half-life has been measured.
Gene: Protein-coding gene on chromosome 19 (45,995,444 to 46,021,318, forward strand). Ensembl gene ENSG00000104983.
Subcellular location: Cytoplasm, cytoskeleton, microtubule organizing center, centrosome; Cytoplasm, cytoskeleton, microtubule organizing center, centrosome, centriolar satellite; Cytoplasm, cytoskeleton, cilium basal body
Subcellular location (Human Protein Atlas): Nucleoplasm
Gene Ontology:
Molecular function: identical protein binding; microtubule binding; protein binding
Biological process: centriole assembly; mitotic spindle assembly
Cellular component: centriolar satellite; centriolar subdistal appendage; centrosome; ciliary basal body; microtubule organizing center
Genetic constraint (gnomAD): Loss-of-function variants: 54 observed, 51.41 expected, observed/expected ratio (o/e) 1.05, 90% interval 0.84 to 1.32. The upper end of that interval is the gene's LOEUF score, 1.32, which puts it in group 5 of 6, group 1 being the genes least tolerant of losing a copy. Missense variants: 649 observed, 627.04 expected, observed/expected ratio (o/e) 1.03, 90% interval 0.97 to 1.1. Synonymous variants: 270 observed, 264.4 expected, observed/expected ratio (o/e) 1.02, 90% interval 0.92 to 1.13.
Homologues: Orthologues: chimpanzee CCDC61 (99% identical), macaque CCDC61 (97% identical), dog CCDC61 (90% identical), guinea pig CCDC61 (86% identical), mouse Ccdc61 (85% identical), pig CCDC61 (84% identical), rat Ccdc61 (84% identical), tropical clawed frog ccdc61 (46% identical), zebrafish ccdc61 (44% identical). Paralogues in human: SPTY2D1 (16% identical).
Diseases named in the same sentence as CCDC61 in open-access papers:
CCDC61 is named in the same sentence as 3 diseases in open-access papers, as found by Europe PMC text mining. Sharing a sentence is not in itself a finding about the gene and the disease. The quoted sentences say what the papers report.
COVID-19 (1 paper, 2022). A disease caused by infection with severe acute respiratory syndrome coronavirus 2. "This suggests that the remaining CpGs (annotated in genes such as CCDC61, CD38, FAM38A, LAT, TREX1 or NFAT5, among others) differentially contribute to similarities between COVID-19 progression and SADs, some of them regulating the activation and differentiation of T and B lymphocytes." (PMID 35933486, 2022).
lung carcinoma (1 paper, 2019). "Of note, the truncated isoform of CCDC61–101, involved in the oncogenic fusions to RET or ROS1 kinases in lung cancer, can form heterodimers with and relocate the wild type protein in the cytosol." (PMID 31877762, 2019).
CCDC61 also shares sentences with these, for which no sentence is quoted: chronic myelogenous leukemia (1 paper).